TIMP1 (TIMP metallopeptidase inhibitor 1)
Diseases named in the same sentence as TIMP1 in open-access papers (continued):
Sharing a sentence is not in itself a finding about the gene and the disease.
Sepsis (53 papers, 2009 to 2025). Sepsis is defined as life-threatening organ dysfunction caused by a dysregulated host response to infection. "Studies show that the serum levels of TIMP1 and MMPs are associated with outcomes in patients with sepsis." (PMID 40864331, 2025). "In patients with sepsis after major abdominal surgery and sepsis-associated organ dysfunction, higher serum TIMP-1 levels were correlated with disease severity, kidney injury and the use of vasopressors/inotropes." (PMID 35197070, 2022). "Other studies have identified other MMP variants as associated with sepsis susceptibility or prognosis: MMP-1, MMP-3, MMP-8, and TIMP-1 variants have already been investigated in sepsis outcome in a few hundred ICU patients with severe sepsis." (PMID 35204780, 2022). "Inclusion of patients with broader criteria would have provided a wider perspective on sepsis susceptibility and interaction with MMPs/TIMP-1 as well as with the Hardy–Weinberg equilibrium." (PMID 35204780, 2022). "MMP-9, TIMP-1, and MMP-9/TIMP ratio were good diagnostic or prognostic biomarkers of sepsis after major abdominal surgery and were linked to sepsis-associated organ dysfunction in rats and humans." (PMID 33488296, 2021). "An association of sepsis-related mortality disease with TIMP-1/MMP-9 ratios was found in several studies for adults and children." (PMID 33488296, 2021). "The MMPs and their inhibitors have been associated with mortality in organ injury and sepsis, where serum levels of TIMP‐1 and TIMP-1/MMP‐9 ratios have been associated with disease severity and mortality." (PMID 31932967, 2021). "TIMP-1 levels also correlated with sepsis-associated coagulopathy, both with the degree of disseminated intravascular coagulation (DIC) and disease severity." (PMID 33488296, 2021). "ROC curve analysis showed that TIMP-1 and MMP-9/TIMP-1 ratio were very good diagnostic biomarkers of sepsis after major abdominal surgery." (PMID 29861795, 2018). "The role of matrix metalloproteinase-9 (MMP-9) and tissue inhibitor of matrix metalloproteinase-1 (TIMP-1) in sepsis after major abdominal surgery and sepsis-associated organ dysfunction is unexplored." (PMID 29861795, 2018). "The association of MMP-9 and TIMP-1 with severity and outcome of sepsis has already been recognised." (PMID 29861795, 2018). "The evaluation of MMP-9, TIMP-1, and MMP-9/TIMP-1 ratio as diagnostic biomarkers of sepsis was performed by the calculation of AUC-ROC values." (PMID 29861795, 2018). "Recently, in a study Involving 192 Patients with severe sepsis it was observed association between TIMP1 / MMP9 ratio and mortality in a predictive model at 30 days follow-up." (PMID 28192449, 2017). "In a recently published study conducted on 53 abdominal surgery patients with sepsis, TIMP-1 appeared to be a possible diagnostic biomarker for sepsis-associated AKI." (PMID 27561093, 2016). "NGAL and TIMP-1 are valuable for the risk stratification, early diagnosis and prognostication of sepsis in the ED." (PMID 25407832, 2014). "The novel findings of our study were that there is an association between the 372 T/C genetic polymorphism of TIMP-1 (rs4898), circulating levels of TIMP-1 and 30-day survival in patients with severe sepsis." (PMID 23706069, 2013). "Of 275 patients with severe sepsis, 80 had genotype CC, 55 had genotype CT and 140 had genotype TT of the 372 T/C genetic polymorphism of TIMP-1." (PMID 23706069, 2013). "The risk of death in sepsis patients with TIMP-1 values greater than 531 ng/ml was 80% higher than that in patients with lower values (RR = 1.80; 95% CI = 1.13 to 2.87;P = 0.01; sensitivity = 0.73; specificity = 0.45)." (PMID 19799791, 2009). "Future studies could possibly provide more insight into MMP-9 and TIMP-1's role in the pathophysiology of the sepsis-associated organ dysfunction." (PMID 29861795, 2018).
Sepsis (continued). "A total of 275 patients with severe sepsis were included, 80 with genotype CC (or male hemizygous C), 55 with genotype CT and 140 with genotype TT (or male hemizygous T) of the 372 T/C genetic polymorphism of TIMP-1 (rs4898)." (PMID 23706069, 2013). "Many causal mechanisms in sepsis susceptibility are largely unknown and the functional genetic polymorphisms (GP) of matrix metalloproteinases (MMPs) and their natural tissue inhibitor of MMPs (TIMP1) could play a role in its development." (PMID 35204780, 2022). "Their findings suggested TIMP1 could serve as potential diagnostic biomarker of sepsis with AKI." (PMID 33863396, 2021). "In contrast, proteins related to the wound healing, such as ACTB, FINC, and TIMP1, showed significant upregulation or downregulation across sepsis subgroups." (PMID 40864331, 2025). "In other conditions, including critically ill patients with AKI and sepsis-associated AKI, high levels of OPN and TIMP-1 herald kidney repair and decrease with successful tissue recovery." (PMID 39440014, 2024). "Hoffmann and collaborators reported elevated levels of matrix metalloproteases and their inhibitors (MMP-9, TIMP-2 and TIMP-1) in severe sepsis, and TIMP-1 was suggested as a useful biomarker in predicting the clinical outcome of patients with severe sepsis." (PMID 37817235, 2023). "Not only this, but MMP‐8 levels have also been evidenced to be increased alongside MMP‐9, MMP‐2, and TIMP‐1 during early sepsis, a condition which has eventually been related to patient mortality." (PMID 35818743, 2022). "Compared with the discriminative ability of serum TIMP-1 for mortality in patients with sepsis, urinary TIMP-1 in our study had a good performance in predicting PICU mortality." (PMID 35197070, 2022). "In vivo, patients with sepsis were found to have high TIMP-1 and low MMP-9 concentrations in serum, which predicted a monocyte-derived increase in TIMP-1 concentrations in peripheral blood." (PMID 36670630, 2022). "The tissue inhibitor of matrix metalloproteinase-1 (TIMP-1) and MMP-9 can be used as potential diagnostic biomarkers for sepsis-associated AKI in clinical assessment." (PMID 36177176, 2022). "In fact, the eventual mortality of patients has been associated with the elevated levels of MMP‐2, MMP‐9, MMP‐8, and TIMP‐1, as observed in the early stages of sepsis." (PMID 35818743, 2022). "It has been indicated that serum TIMP-1 has a higher level in septic patients with AKI and is a good diagnostic biomarker of sepsis-associated AKI." (PMID 35197070, 2022). "Matrix metalloproteinase-8 (MMP-8) and tissue inhibitor of metalloproteinases-1 (TIMP-1) have been shown to predict prognosis in sepsis." (PMID 34043679, 2021). "On the other hand, serum levels of TIMP1 were previously reported to be elevated in patients with various cancers, myocardial infarction, ischemic stroke, and sepsis." (PMID 33743769, 2021). "The present study observed significantly higher early MMP-8 (day 3 and 5) and TIMP-1 (day 3) levels among patients with severe sepsis, high Pitt bacteremia scores and ICU treatment compared to patients without severe illness or need for ICU." (PMID 34043679, 2021). "MMP-2 has been shown to be involved in inflammation, recruitment of inflammatory cells, permeability and remodeling in lung and TIMP-1 has been studied as a prognostic factor for sepsis." (PMID 34502521, 2021). "In this study, we aimed to evaluate the diagnostic value of several MMPs (MMP-2, MMP-9, MMP-8) and TIMPs (TIMP-1 and TIMP-2) for equine colic, which is often associated with endotoxemia and sepsis in case of strangulating obstruction." (PMID 33488296, 2021). "ROC analyses were used to find the optimal cutoff of MMP-9 as well as TIMP-1 concentrations to identify animals with positive sepsis scoring (≥10/19 points)." (PMID 33488296, 2021).
Sepsis (continued). "They concluded that a higher TIMP-1/MMP‐9 ratio was associated with severity, coagulation state, circulating cytokine levels and mortality and proposed it as an outcome biomarker of sepsis." (PMID 31932967, 2021). "The results indicate that MMP-9, TIMP-2, and TIMP-1 showed the higher sensitivity, specificity, and positive predictive value for sepsis." (PMID 31671729, 2019). "MMP-9, TIMP-2 and TIMP-1 have been shown to be elevated in patients with severe sepsis and septic shock as well as in animal models of endotoxemia, while MMP-1, MMP-8 and MMP-13 have also been associated with sepsis." (PMID 30466423, 2018). "MMP-9, TIMP-1, biomarkers of inflammation, kidney and liver injury, coagulation, and metabolic disorders were measured daily during 96 h following diagnosis of sepsis and once in controls." (PMID 29861795, 2018). "MMP-9, TIMP-1, and MMP-9/TIMP ratio were good diagnostic or prognostic biomarkers of sepsis after major abdominal surgery and were linked to sepsis-associated organ dysfunction." (PMID 29861795, 2018). "On the other hand, elevated MMP-9 and TIMP-1 expression was found in kidneys and livers of animal models of sepsis." (PMID 29861795, 2018). "The level of circulating TIMP1 was reportedly elevated in patients with myocardial infarction, sepsis, and various cancers." (PMID 28962592, 2017). "The most prominently induced was tissue MMP inhibitor 1 (TIMP1), which was 6.34-fold increased in sepsis and 4.52-fold decreased in compstatin-treated septic baboons, as shown by qPCR." (PMID 26337158, 2015). "Compstatin treatment downregulated multiple sepsis-induced regulators of extracellular matrix remodelling; TIMP1 decreased by >fourfold in the compstatin-treated group." (PMID 26337158, 2015). "It is reported that MMP-9 and gelatinase activity increased significantly after sepsis, and TIMP-1, an MMP-9 inhibitor, blocked these activities, as well as the ensuing septic shock." (PMID 25407832, 2014). "Matrix metalloproteinase-9 (MMP-9) and its inhibitor, tissue inhibitor of matrix metalloproteinase-1 (TIMP-1), are promising novel biomarkers to predict the severity and outcome of sepsis, and are involved in the pathogenesis of sepsis and septic shock." (PMID 25407832, 2014). "In our study, TIMP-1 levels significantly increased on admission according to the severity of sepsis." (PMID 25407832, 2014). "Elevated levels of MMP-9 and TIMP-1 were reported in septic patients, and higher TIMP-1 levels at the beginning of severe sepsis were predictive of death." (PMID 25407832, 2014). "Recently Lorente and colleagues reported elevated MMP-10 and TIMP-1 levels in the beginning of severe sepsis." (PMID 20356362, 2010). "An association was found between MMP-9, MMP-10, TIMP-1, and MMP-9/TIMP-1 ratios and parameters of sepsis severity, assessed by the SOFA score, the APACHE-II score, lactic acid, platelet count, and markers of coagulopathy." (PMID 19799791, 2009). "The objective of this study was to determine the predictive value of MMP-9, MMP-10, and TIMP-1 on clinical severity and mortality in a large series of patients with severe sepsis." (PMID 19799791, 2009). "Previous studies with small sample sizes (fewer than 40 patients) have shown higher levels of MMP-9 and TIMP-1 in sepsis patients than in controls." (PMID 19799791, 2009). "Several other products implicated in the pathogenesis of sepsis were also induced by this treatment, including IL-12p40, CCL5/RANTES, CXCL1/KC, CCL9/MIP-1γ, CXCL2/MIP-2, P-Selectin, TIMP-1 and CCL2/MCP-1." (PMID 19284588, 2009). "The intersection of databases RM2Target, GSE179554-6 h, and GSE179554-12 h presented 7 genes (Mt1, Mt2, Alpl, Angptl4, Apod, Slc7a5, and Timp1) that may bind towards YTHDC1 in sepsis." (PMID 38842666, 2024). "NGAL and TIMP-1 are valuable for early diagnosis of sepsis in the ED." (PMID 36878489, 2023). "Additionally, serum levels of MMP-8 and TIMP-1 were correlated with mortality in patients with sepsis." (PMID 36142454, 2022).
Sepsis (continued). "GPs of MMPs and TIMP (namely MMP-1 rs1799750, MMP-3 rs3025058, MMP-8 rs11225395, MMP-9 rs2234681, and TIMP-1 rs4898) have been compared in 1058 patients with suspected sepsis to assess the association with susceptibility and etiology of sepsis." (PMID 35204780, 2022). "In the study of sepsis-associated acute kidney injury (SA-AKI), septic patients had higher serum TIMP-1 levels which could serve as a potential diagnostic biomarker of SA-AKI." (PMID 33777519, 2021). "Several earlier studies have reported high levels of TIMP-1 in patients with sepsis." (PMID 32190734, 2020). "There are several reports demonstrating an increase in MMP-9 and TIMP-1 levels in sepsis." (PMID 32190734, 2020). "Furthermore, TIMP-1 has been confirmed to be a predictor of clinical outcomes in patients with severe sepsis, while TIMP-2 is regarded as an early biomarker for predicting acute kidney injury (AKI), which is a common complication of sepsis." (PMID 31671729, 2019). "Sepsis-associated lung injury is linked to elevated MMP-9 and TIMP-1 lung expression, but mechanical ventilation per se is related to reduction in MMP-9 and TIMP-1 levels." (PMID 29861795, 2018). "TIMP-1, unlike MMP-9 and MMP-9/TIMP-1 ratio, was a good diagnostic and prognostic biomarker of sepsis after major abdominal surgery." (PMID 29861795, 2018). "It is important to take into account that levels of TIMP1 in septic patients have been significant predictors of mortality in multivariate models, which suggests a crucial role of this biomarker in the pathophysiology and outcome of sepsis." (PMID 28192449, 2017). "The median levels of serum NGAL and TIMP-1 increased with sepsis severity." (PMID 25407832, 2014). "A novel finding of the current study was that TIMP-1/MMP-9 ratio during the first week could be used as a biomarker of sepsis outcome according to the results of ROC curve analysis." (PMID 24727739, 2014). "In a previous study by our team we found that TIMP-1 levels at the time of severe sepsis diagnosis could be used as a biomarker of sepsis outcome." (PMID 24727739, 2014). "In addition, an association between circulating TIMP-1 and plasminogen activator inhibitor (PAI)-1 levels in septic patients at severe sepsis diagnosis has been reported." (PMID 24727739, 2014). "The objective of this study was thus to determine whether there is an association between the 372 T/C genetic polymorphism of TIMP-1, serum levels of TIMP-1 and survival in patients with severe sepsis." (PMID 23706069, 2013). "Thus, the objective of this study was to determine the influence of the circulating levels of MMP-9, MMP-10, and TIMP-1 on the severity and mortality of patients with sepsis in a large cohort." (PMID 19799791, 2009). "Therefore, besides the already known higher mortality rate in sepsis patients with increased lactic acid levels and SOFA score, our results suggest that alterations in the MMP-9/TIMP-1 ratio and MMP-10 levels are associated with the severity of sepsis." (PMID 19799791, 2009). "MMP-9 and TIMP-1 are key regulators of inflammation, and disturbances in their dynamic balance of expression and activity may contribute to tissue damage and increased mortality in sepsis." (PMID 38337856, 2024). "Moreover, TIMP1 levels in serum have been found to be increased in severe sepsis in humans." (PMID 37175585, 2023). "Another observational study that used the older sepsis definition, systemic inflammatory response syndrome (SIRS) criteria, found the diagnostic performance of neutrophil gelatinase-associated lipocalin (NGAL) and tissue inhibitor of matrix metalloproteinases-1 (TIMP-1) greater than PCT in the ED." (PMID 36878489, 2023). "Thus, these previous studies combined with the strong increase in PMVEC Timp1 expression seen in our dual stimulation in vitro, as well as in PMVEC isolated from mice with CLP-sepsis in vivo, strongly suggest a potential role for PMVEC-specific TIMP1 in tissue injury and sepsis." (PMID 37175585, 2023).
Sepsis (continued). "TIMP1 could be used as prognostic marker for the onset of sepsis." (PMID 32174955, 2020). "A more detailed comment on the role of these biomarkers in septic AKI could be found in our earlier paper, but clinical reports on MMP-9 and TIMP-1 in sepsis-associated liver injury are lacking." (PMID 29861795, 2018). "The objectives of this study were to investigate, for the first time, MMP-9, TIMP-1, and the MMP-9/TIMP-1 ratio as diagnostic and prognostic biomarkers of sepsis after major abdominal surgery as well as the potential relationships between these biomarkers and sepsis-associated organ dysfunction." (PMID 29861795, 2018). "Therefore, and considering the size of the patient population and the multivariate prediction model of mortality used here, it could be argued that plasma levels of TIMP1 should be considered as a promising prognostic biomarker in the setting of sepsis." (PMID 28192449, 2017). "Similarly, semi-quantitative immunofluorescence analysis of lung tissues stained for TIMP1 supports the mRNA and protein quantification, with specimens from the sepsis group being stronger stained for TIMP1, while compstatin-treated baboons showed significantly lower staining." (PMID 26337158, 2015). "However, the relationship between genetic polymorphisms of TIMP-1, circulating TIMP-1 levels and survival in patients with severe sepsis has not been examined, and this was the objective of the study." (PMID 23706069, 2013). "However, the relationship between genetic polymorphism of TIMP-1, circulating TIMP-1 levels and survival in patients with severe sepsis has not been examined." (PMID 23706069, 2013). "However, an association between the 372 T/C genetic polymorphism of TIMP-1 and survival in patients with severe sepsis has not been previously reported." (PMID 23706069, 2013). "• TIMP-1 levels may represent a biomarker to predict the clinical outcome of sepsis patients." (PMID 19799791, 2009). "In contrast, a novel set of biomarkers, including ACTB, FINC, CXCL7, TIMP1, and PF4, was identified for sepsis prognosis." (PMID 40864331, 2025). "Five key proteins—β-actin (ACTB), fibronectin (FINC), metalloproteinase inhibitor 1 (TIMP1), platelet factor 4 (PF4), and C-X-C motif chemokine 7 (CXCL7)—were identified as significant discriminators of sepsis subgroups with AUCs ranging from 0.786 to 0.833." (PMID 40864331, 2025). "In contrast, ACTB, FINC, TIMP1, PF4, and CXCL7 showed greater potential for predicting sepsis outcomes." (PMID 40864331, 2025). "A novel set of biomarkers was identified in this study, including ACTB, FINC, CXCL7, TIMP1, and PF4, for assessing sepsis prognosis." (PMID 40864331, 2025). "In recent decades, several new early biomarkers for sepsis have been tested, such as matrix metalloproteinase-9 (MMP-9), its endogenous inhibitor tissue inhibitor of metalloproteinase-1 (TIMP-1), and mid-regional pro-adrenomedullin (MR-proADM)." (PMID 38337856, 2024). "Severe COVID-19 shared many characteristics with sepsis and plasma MMP-9 and tissue inhibitor of matrix metalloproteinase-1 (TIMP-1) have been also proposed as septic biomarkers." (PMID 36523781, 2022). "Higher MMP-2, MMP-8, MMP-9, MMP-10, TIMP-1 and MMP-10/TIMP-1 were seen in severe sepsis compared to controls." (PMID 34043679, 2021). "Previously, MMP-9, TIMP-1 levels, and MMP-9/TIMP-1 ratio have been suggested as biomarkers in adult severe sepsis and septic shock." (PMID 33748037, 2021). "Patients with sepsis had higher TIMP-1 levels and lower MMP-9/TIMP-1 ratios than both control groups at all time points." (PMID 29861795, 2018). "Compared with the healthy control group, NGAL, MMP-9 and TIMP-1 levels were significantly higher in patients with SIRS, sepsis, severe sepsis and septic shock (P <0.01)." (PMID 25407832, 2014). "The strengths of our study were the large sample size and the follow-up of circulating TIMP-1, MMP-9, TNF-alpha, IL-10, and PAI-1 levels throughout the first week after diagnosis of severe sepsis." (PMID 24727739, 2014).